TNF (tumor necrosis factor)
Diseases named in the same sentence as TNF in open-access papers (continued):
Sharing a sentence is not in itself a finding about the gene and the disease.
COVID-19 (continued). "Higher plasma IL-6 and TNFα levels may trigger platelet activation and coagulation, and in turn aggravate thrombosis and hypercoagulation in severe COVID-19 patients." (PMID 38709269, 2024). "Similarly, increased INF-γ and TNF-α levels in COVID-19 patients corroborate findings from other research indicating heightened immune activation and inflammation in response to SARS-CoV-2 infection." (PMID 39407725, 2024). "Changes in the level of TNF-α can predict COVID-19 progression, lung damage, and disease severity." (PMID 39273479, 2024). "The study highlights the intricate balance of TNF and its receptors in COVID-19 pathogenesis." (PMID 39335653, 2024). "FDA-approved TNFα and IL-6 inhibitors have shown clinical promise in COVID-19 treatments." (PMID 38251382, 2024). "Plasma sampling from patients with severe COVID-19 has revealed high circulating levels of immune-inflammatory markers such as interleukin (IL)-6, IL-1β, IL-2, IL-7, IL-17, and tumor necrosis factor (TNF)-α; this is also the reason behind the anti-inflammatory treatments used for COVID-19 pneumonia." (PMID 38532424, 2024). "At D3, PRR signaling pathways like cytosolic DNA sensing, RIG-I-like receptor signaling, and Toll-like receptor signaling dominated the pro-inflammatory cytokine production-related signaling pathways, like TNF signaling, and several virus pathways, including coronavirus disease—COVID-19." (PMID 39057755, 2024). "Polymorphisms in the TNF and IFNG genes, particularly those related to the regulation of their expression, are natural candidates to play a role in the pathogenesis and evolution of COVID-19." (PMID 38675991, 2024). "For this reason, the present study investigated the association of two single nucleotide polymorphisms (SNPs), TNF -308G/A (rs1800629) and IFNG +874T/A (rs2430561), with aspects of COVID-19 severity, becoming the first study to investigate the association of IFNG +874T/A with this infection." (PMID 38675991, 2024). "During cytokine storms in patients with COVID-19, interleukin (IL)-6 and tumor necrosis factor (TNF)-α have been used to reduce suppressive functions of T regulator cells, resulting in an increase in IL-17 and reduction in interferon (IFN)-γ expression in inflamed tissue." (PMID 39861800, 2024). "The cytokine storm in COVID-19 is characterized by a high expression of IL-6 and TNF-α." (PMID 39685929, 2024). "One possibility for the origin of the COVID-19 pro-inflammatory state is Cystic Fibrosis, a rare, lethal, pro-inflammatory genetic disease, which is characterized by coincident and sustained activation of proinflammatory TNFα/NFκB and ENaC signaling." (PMID 39043712, 2024). "Similarly, matrine, another natural compound, inhibits COVID-19 virus replication and promotes the apoptosis of infected cells by altering TNF-α and IL-6 levels and increasing caspase-3 expression." (PMID 38276618, 2024). "Because of the imbalance in the immune system, patients with autoimmune thyroid disorders may have more severe COVID-19 than healthy individuals due to higher baseline serum concentrations of IL-6 and TNF-α." (PMID 39045269, 2024). "Future research should focus on more targeted trials that include homogenous patient groups to ascertain the specific patient profiles that might benefit from TNF inhibition in COVID-19." (PMID 39459457, 2024). "According to research, COVID-19 may promote oxidative stress through some important pathways, for example, the TNF-α and NF-κB pathways." (PMID 38622314, 2024). "Moreover, they revealed an “IFN-I-potentiated TNF/IL-1β inflammatory response” in severe/fatal COVID-19 using scRNA-seq analysis, which further clarified the pro-inflammatory role of IFN-I." (PMID 39148728, 2024).
COVID-19 (continued). "The expression level of TNFα signaling via NF-κB signaling pathway-related genes was comparable in COVID-19 naive individuals and COVID-19 convalescents before vaccination, but that level was significantly higher in convalescents than in COVID-19 naive individuals after vaccination." (PMID 38319108, 2024). "The principle for examining cytokine storm in COVID-19 includes a decline in blood lymphocyte count and elevated systematic inflammatory indicators, along with multiple cytokines, such as IL-1β, IL-6, and TNF-α." (PMID 37742314, 2024). "Cytokine storm syndromes, such as those seen in COVID-19, are reflected in TNF-α and IFN-γ shock." (PMID 38727220, 2024). "It has been shown that proinflammatory cytokines and chemokines, including IL-1β, TNF-α, IL-6, interferon gamma-induced protein-10, monocyte chemoattractant protein-1, and macrophage inflammatory proteins 1-α, were significantly elevated in COVID-19 patients." (PMID 39195168, 2024). "The role of serological components in causing cardiovascular damage in COVID-19 is further corroborated by a significant negative correlation of IL-6, TNF-α, IL-1β, IL-10, and CRP levels with cardiomyocyte viability." (PMID 38041432, 2024). "Additionally, both genes were significantly upregulated in the severe COVID-19 group compared to the moderate group (p = 0.0004 for IL-1ß; p = 0.0004 for TNF-α)." (PMID 38183501, 2024). "For example, the upregulation of TNF-α and IL-6, two major cytokines in COVID-19, directly affects brain physiology and may negatively promote stress-related responses such as mood alterations." (PMID 39205157, 2024). "Thus, tumor necrosis factor-α (TNF-α) and interferon-induced transmembrane (IFITM) proteins have also been associated with severe COVID-19 and higher inflammatory states." (PMID 38400050, 2024). "Also, increased expression levels of IL-6 and TNFα were found in the lung biopsy of a severely ill patient with COVID-19 who subsequently died." (PMID 39457048, 2024). "Several studies have shown a significant association between high levels of Gal3 in the blood serum and COVID-19 severity, along with increased pro-inflammatory cytokines (IL-1β, TNF-α, and IL-12), chemokine C-C, and chemokine receptor type 5 (CCR5) expression in T cells." (PMID 39125989, 2024). "In COVID-19 patients, abnormal activation of macrophages expressing M1/M2 polarization markers (CD68, CD80, CD163, and CD206) in the lung is associated with the production of cytokines, including IL-6, IL-10, and TNF-α, as indicated by previous studies." (PMID 39100091, 2024). "Hyperactivation of pro-inflammatory type 1 cytokines (e.g., tumor necrosis factor alpha [TNF-α] and interferon gamma [IFN-γ]) mirrors the inflammation of coronavirus disease 2019." (PMID 38727220, 2024). "To investigate whether lymphocyte depletion in patients with severe COVID-19 is associated with cytokine levels, we correlated lymphocyte levels in patients with severe COVID-19 with their IL6, IFN γ, and TNF-α levels." (PMID 39407725, 2024). "In our cohort, TNF-α was elevated in mild COVID-19 and decreased with severity." (PMID 38791465, 2024). "COVID-19 as a viral infection, is characterized by unique hyperinflammatory signatures across all types of immune cells, among which is the upregulation of IL-1β-, IL-6, and TNF-α-driven inflammatory responses, especially in severe cases." (PMID 38183501, 2024). "In severe COVID-19 patients, the hyperinflammatory response, also called the cytokine storm, is a hallmark feature with elevated circulating levels of IL-2/4/6/10, STAT1/2/3, and TNF-a." (PMID 38257800, 2024). "Therefore, the aim of the current study was to investigate the association between the IL-6 rs1800796, IL-10 rs1800896, TNF-α rs1800629, and IFITM3 rs12252 polymorphisms and the presence of post-COVID symptoms in previously hospitalized COVID-19 survivors." (PMID 38400050, 2024). "TNF-alpha has also been shown to play a vital role in inflammatory cell death in COVID-19." (PMID 38539805, 2024).
COVID-19 (continued). "Severe COVID-19 cases are characterized by an increase in pro-inflammatory cytokines plasma levels, especially interleukins IL-1β, IL-2, IL-6, IL-7, and IL-10 granulocyte-macrophage colony-stimulating factor (GM-CSF) and tumor necrosis factor-alpha (TNF-a)." (PMID 37445296, 2023). "Type I IFN responses occurred simultaneously with inflammatory responses driven by TNFα and IL-1β in classical monocytes from patients with severe COVID-19, suggesting that type I IFNs may play an important role in exacerbation." (PMID 37108051, 2023). "Moreover, hyperactivation of the PI3K-Akt signaling pathway is involved in viral entry into cells and in the induction of pro-inflammatory mediators (TNF-α, IL-6, etc.)that significantly contribute to the etiology of COVID-19." (PMID 36817449, 2023). "It has been described previously that infection with COVID-19 triggers a systemic immune response in the human body, manifested by increased expression of proinflammatory cytokines, including interleukins (IL-1, 6, 8) and tumor necrosis factor α (TNFα)." (PMID 37762413, 2023). "Finally, we found that monocytes from convalescent COVID-19 patients produced less TNF-α and IL-6 in response to LPS stimulation, than those from uninfected controls." (PMID 38250080, 2023). "Importantly, macrophages are one of the main sources of proinflammatory cytokines such as IL-6 and TNF and were found to play a central role in the pathology of severe COVID-19." (PMID 37253946, 2023). "IL-6, TNF-α, and IL-10 may especially be related to cytokine storms in neonates of mothers with COVID-19." (PMID 36979888, 2023). "Lactiplantibacillus plantarum is a probiotic that was reported to modulate cytokine production by increasing TNF-α, IL-1β, IL-18, and IL-8, and reducing IL-6, a critical factor in immune dysregulation in COVID-19, thus enhancing the activity of natural killer cells." (PMID 37298539, 2023). "However, it was surprising that TNF-α levels were lower in the saliva in patients with COVID-19 induced xerostomia." (PMID 36846089, 2023). "Of those, IL-8, IL-6 and TNF-α were the most enhanced in HD + COVID-19 patients." (PMID 36675231, 2023). "Also, a depletion of CD56dim and CD56bright NK cells, involved in cell-mediated cytotoxicity and production of cytokines (IFN-γ and TNF-α), has been reported in severe COVID-19 patients." (PMID 37065291, 2023). "It is, therefore, speculated that anti-inflammatory interventions targeting TNF-α can benefit COVID-19 patients, especially in preventing irreversible lung injury." (PMID 37047115, 2023). "Notably, the inhibition of HSP90 has been observed to decrease the production of significant pro-inflammatory cytokines, including IL-1β, IL-6, CXCL10, and tumor necrosis factor (TNF), which are implicated in the progression of COVID-19." (PMID 37630994, 2023). "Thus, it can be expected that the combination of chitosan, chitosan oligosaccharides, and polyphenols can prevent the development of severe COVID-19 due to the inhibition of NF-κB and TNF-α, which lead to the increase of tissue stiffness and permeability." (PMID 36674700, 2023). "By comparing our data with published transcriptome of severe acute respiratory syndrome coronavirus 2 infections in other cell lines, the common function of monkeypox and COVID-19 includes cytokine signaling in the immune system, TNF signaling, and MAPK cascade regulation." (PMID 37006463, 2023). "The hyperinflammatory COVID-19 response is mediated, at least partially by the rapid proliferation and/or activation of immune cells and overproduction of pro-inflammatory cytokines, such as interleukin 6 (IL-6) and the tumour necrosis factor (TNF)." (PMID 36791125, 2023). "Finally, ROC curve results uncovered that IL-10, IL-23 and TNF-α were excellent predictors for prognosing COVID-19." (PMID 37283736, 2023).
COVID-19 (continued). "Cholesterol has been linked to proinflammatory effects that were hypothesized may lead to poor COVID-19 outcomes due to activation of macrophages and dysregulation of NF-κB and TNF alpha pathways." (PMID 36829115, 2023). "Moreover, in contrast to what has been described, levels of TNF and IL-1β are found to be significantly reduced in our whole cohort of COVID-19 patients." (PMID 36861136, 2023). "Prior reports have noted diverse triggers, including vaccines (e.g., hepatitis B, tetanus, and Bacillus Calmette–Guérin), viral infections (e.g., varicella, herpes zoster, and COVID-19), medications (e.g., allopurinol, amlodipine, and anti-TNF agents), trauma, arthropod bites, and malignancy." (PMID 38106989, 2023). "In the case of COVID-19, the cytokines involved in cytokine storm mainly include tumor necrosis factor-alpha (TNF-α), interleukin 1β (IL-1β), interleukin 6 (IL-6), interleukin 8 (IL-8), interleukin 10 (IL-10), interferon alpha (IFN-α), and granulocyte-macrophage colony-stimulating factor (GM-CSF)." (PMID 37841241, 2023). "Furthermore, TNF inhibitors such as golimumab and adalimumab have gained popularity in the treatment of severely infected patients with COVID-19." (PMID 36679947, 2023). "IL-6, IL-1β, and TNF-α are all key cytokines in both COVID-19 and RA." (PMID 37163438, 2023). "Recently, COVID-19 patients were shown to have higher levels of Gal-3, TNF-α, IL-1β, and IL-6." (PMID 37112643, 2023). "Furthermore, specific TNF-α and TNF-β gene polymorphisms increase the risk of COVID-19 occurrence and severity." (PMID 36928185, 2023). "Additionally, other cytokines, such as TNF-α, IFN-γ, and IL-1β, have also been implicated in the cytokine storm observed in COVID-19 patients and can contribute to increased inflammation and hypercoagulability." (PMID 36901751, 2023). "In this group, we consistently observed strong correlations of IL-5 with IFN-γ and IL-1β with TNF-α, supporting the hypothesis of synergistic Th1 and Th2 responses and cooperative activity between type 1 and type 2 macrophages in controlling COVID-19." (PMID 37047752, 2023). "Association and clustering analysis reveals that the “HQ + FF + BZ” drug combination had a strong correlation and confidence in 93 TCM prescriptions and may affect the progression of COVID-19 through inflammatory pathways such as the TNF signaling pathway." (PMID 38050310, 2023). "Consequently, patients with severe COVID-19 have considerably higher blood levels of IL-2, IL-6, TNF-α, IL-1, IL-10, IFN-γ, IL-8/CXCL8, and CXCL10/IP-10 during the cytokine storm, potentially because of NF-κB via selective activation." (PMID 36851766, 2023). "Interestingly, two adipocytokines, IL-6 and tumor necrosis factor-alpha (TNFα), are related to COVID-19 severity and patients’ death." (PMID 38110483, 2023). "Some elevated cytokine levels, such as interleukin-6 (IL-6), tumor necrosis factor (TNF), interferons (IFNs), granulocyte-macrophage colony-stimulating factor (GM-CSF), and interleukin-18 (IL-18), are often reported in severe-critical patients with COVID-19." (PMID 36679421, 2023). "Moreover, significant positive association has been observed among increased IL-10, IL-23 and TNF-α in serum of COVID-19 patients." (PMID 37283736, 2023). "Notably, the correlations of T helper naïve and effector memory cells, T helper 1–17 cells, TNF, IL-10, IL-1β, IL-8, among others, showed differences between healthy controls and COVID-19 patients." (PMID 36861136, 2023). "A high incidence of lymphopenia, ranging from 67–75%, has been consistently reported among COVID-19 patients who have a severe illness; it may correlate with an increased quantity of cytokines such as IL-6, IL-10 or TNF (tumor necrosis factor)." (PMID 37754237, 2023). "Second, some inflammatory markers associated with critical cases of COVID-19, such as IL-6, interleukin (IL)-1β, and TNF-α, were not included." (PMID 36999038, 2023).
COVID-19 (continued). "Studies of COVID-19 patients also showed significant increases in proinflammatory cytokines and chemokines, including IL-6, IL-1β, TNF-α, and granulocyte–macrophage colony-stimulating factor, in patients’ plasma, with much higher levels in the plasma of critically ill patients." (PMID 37628764, 2023). "The frequency of specific TNF-α induced by the Mix-VLPs with the adjuvant in the current study is similar to that reported in clinical trials of COVID-19 vaccines such as SARS-CoV-2 FINLAY-FR-1A dimeric-RBD recombinant vaccine and recombinant spike protein nanoparticle vaccine." (PMID 36901827, 2023). "The clinical symptoms of COVID-19 relate to several cytokines including interleukin (IL)-2, IL-7, IL-10, tumor necrosis factor (TNF) with IL-6, IL-6-signal transducer and activator of transcription 3 (STAT3) and nuclear factor kappa B (NF-κB) pathway being of high significance." (PMID 36987476, 2023). "COVID-19 and RA coexist with TNF-α and IL-1 to activate the NF-κB pathway." (PMID 37163438, 2023). "We identified nine GO terms associated with the pathway, which could result in upregulation of inflammatory cytokines, such as IL-6 and TNF-α, and contribute to severe cardiac and pulmonary injury in COVID-19 patients." (PMID 38065980, 2023). "Since TNF-α plays an important role in promoting ARDS, obese patients, who are already characterized by elevated TNF-α levels, have higher risk of developing a more severe COVID-19 phenotype." (PMID 37686837, 2023). "TNFα contributes to organ damage and predicts poor outcomes in COVID-19 patients." (PMID 38313435, 2023). "Measurement of serum TNFα levels resulted in almost three-fold-higher values in vaccinees (1009.14 ± 296.17 pg/mL) compared to healthy (339.62 ± 37.60 pg/mL) subjects and patients with severe COVID-19 (350.01 ± 264.70 pg/mL, p < 0.001)." (PMID 38137381, 2023). "Among them, the surplus levels of IFN-γ, TNF-α, IL-1, and IL-6 have been known to be associated with the dysfunction of the blood–brain barrier (BBB) as a part of priming the neuroinflammatory process in the human brain during COVID-19." (PMID 36672177, 2023). "Among them, the association of the detected BPs (inflammatory response, response to virus, regulation of inflammatory response, response to tumor necrosis factor, response to cytokine) with COVID-19 and IPF diseases were supported by several independent studies." (PMID 36949176, 2023). "Several signaling pathways are intertwined by the activity of TNF-α, IL-6, and L-10, which may contribute to triggering sudden mucus hypersecretion along with other mediators of the COVID-19 cytokine storm." (PMID 38193087, 2023). "Moreover, anti-TNF therapies seem to have had a protective effect on the progression of COVID-19, especially in severe cases of COVID-19, although this needs to be confirmed." (PMID 37342247, 2023). "This study aimed to address the level of three cytokines which were interleukin-1-beta (IL-1β), interleukin-6 (IL-6), and tumour necrosis factor-alpha (TNF-α), with different blood parameters to the formation of cytokine storm or any complication among COVID-19 patients." (PMID 37363608, 2023). "Several AAbs such as those related to extracellular matrix proteins, TNF-related, centromere-related, and other miscellaneous AAbs changed significantly in the post-COVID-19 samples relative to pre-COVID-19 samples and remained sustained in the subsequent longitudinal PoC2 and PoC3 samples." (PMID 37896822, 2023). "One of the first studies to evaluate the serum cytokine storm in COVID-19 patients showed that several pro-inflammatory mediator levels, such as TNFα, IL-2, IL-7, IL-10, G-CSF, CXCL10, CCL2 and CCL3, were increased in ICU (n = 13) compared to non-ICU COVID-19 patients (n = 28)." (PMID 36941580, 2023).